BEND3 (BEN domain containing 3)
Description:
Transcriptional repressor which associates with the NoRC (nucleolar remodeling complex) complex and plays a key role in repressing rDNA transcription. The sumoylated form modulates the stability of the NoRC complex component BAZ2A/TIP5 by controlling its USP21-mediated deubiquitination. Binds to unmethylated major satellite DNA and is involved in the recruitment of the Polycomb repressive complex 2 (PRC2) to major satellites (By similarity). Stimulates the ERCC6L translocase and ATPase activities.
Synonyms: KIAA1553
Tractability: PROTAC: UniProt records ubiquitination sites on it; ubiquitination databases record sites on it.
Gene: Protein-coding gene on chromosome 6 (107,065,138 to 107,116,234, reverse strand). Ensembl gene ENSG00000178409.
Subcellular location: Nucleus; Nucleus, nucleolus
Subcellular location (Human Protein Atlas): Nucleoplasm
Gene Ontology:
Molecular function: protein binding; rDNA binding; DNA binding
Biological process: DNA methylation-dependent constitutive heterochromatin formation; negative regulation of transcription by RNA polymerase II; positive regulation of ATP metabolic process; protein homooligomerization; rDNA heterochromatin formation
Cellular component: heterochromatin; nucleolus; nucleus
Genetic constraint (gnomAD): Loss-of-function variants: 13 observed, 60.92 expected, observed/expected ratio (o/e) 0.21, 90% interval 0.14 to 0.34. The upper end of that interval is the gene's LOEUF score, 0.34, which puts it in group 1 of 6, group 1 being the genes least tolerant of losing a copy. Missense variants: 896 observed, 1,177.2 expected, observed/expected ratio (o/e) 0.76, 90% interval 0.72 to 0.8. Synonymous variants: 497 observed, 508.98 expected, observed/expected ratio (o/e) 0.98, 90% interval 0.91 to 1.05.
Homologues: Orthologues: chimpanzee BEND3 (99% identical), macaque BEND3 (99% identical), pig BEND3 (95% identical), dog BEND3 (94% identical), rabbit BEND3 (93% identical), guinea pig BEND3 (93% identical), rat Bend3 (92% identical), mouse Bend3 (91% identical), tropical clawed frog pdss2 (69% identical), zebrafish bend3 (53% identical).
Diseases named in the same sentence as BEND3 in open-access papers:
BEND3 is named in the same sentence as 14 diseases in open-access papers, as found by Europe PMC text mining. Sharing a sentence is not in itself a finding about the gene and the disease. The quoted sentences say what the papers report.
breast carcinoma (3 papers, 2016 to 2023). "In summary, BEND3 is a significant gene highly associated with CD24 in breast cancer, and serves as a potential therapeutic target." (PMID 36882451, 2023). "Bend3 endothelial and Neu oncogene induced mammary tumour cell lines were used as constitutively high Dlc1 expressing cell types." (PMID 26977077, 2016). "However, the molecular mechanism of BEND3 in the initiation, development of breast cancer remains unclear." (PMID 36882451, 2023). "BEND3 is a nuclear protein and transcriptional repressor that associates with the HP1-containing heterochromatin loci, and might play a role in identifying the subgroup of breast carcinoma patients with potential to develop visceral metastasis." (PMID 36185995, 2022). "Finally, the roles of BEND3 and SIM2 in tumor immune microenvironment in breast cancer was obtained using online web tools, which requires more experimental validations." (PMID 36882451, 2023).
colorectal cancer (1 paper, 2025). A primary or metastatic malignant neoplasm that affects the colon or rectum. "Survival analysis of differentially expressed longevity-related genes in colorectal cancer found that the expression of 18 genes, including RAD50, ELOVL6, and BEND3, had a greater impact on patient survival." (PMID 40426913, 2025).
glioma (1 paper, 2017). A benign or malignant brain and spinal cord tumor that arises from glial cells (astrocytes, oligodendrocytes, ependymal cells). "However we here showed that a co-culture with rat C6 glioma cells impaired the integrity of ECV304 and bEnd3 cell layers." (PMID 29059256, 2017).
influenza (1 paper, 2014). An acute viral infection of the respiratory tract, occurring in isolated cases, in epidemics, or in pandemics; it is caused by serologically different strains of viruses (influenzaviruses) designated A, B, and C, has a 3-day incubation period, and usually lasts for 3 to 10 days. "Whether any changes occurred in the proportion of BEND3+ T cells was also examined before and after an influenza vaccination." (PMID 25400923, 2014).
lung carcinoma (1 paper, 2013). "To elucidate the role of cPLA2 in both the endothelial cells and lung cancer cells, we investigated how PLA-695 affects proliferation in LLC, A549, bEND3 and HUVEC cells." (PMID 23894523, 2013).
melanoma (1 paper, 2018). A malignant, usually aggressive tumor composed of atypical, neoplastic melanocytes. "The treatment of B16 melanoma cells with Bend3-derived CM resulted in a significant increase in the melanin content and melanogenesis." (PMID 29523807, 2018).
tumor (5 papers, 2019 to 2025). "We plated bEND3-COUP-TFII or control vector-transduced bEND3 cells on the transwell inserts, and quantified the ability of the endothelial cell monolayers to support T cell transwell migration to PyMT tumor cells in the bottom wells." (PMID 40796746, 2025). "Of note, BEND3-knockout cells exhibited a tumor growth rate in vivo comparable to that of control cells in vehicle-treated mice, which is consistent with proliferation data observed in vitro." (PMID 33476303, 2021). "The identified gene expression signature included 14 genes, five (CDYL, ATP6V0A4, PREP, RTN41P1, BEND3 and Kif18A) of which were up-regulated in the group of primary tumours of the patients with visceral organ metastasis." (PMID 30961553, 2019).
cancer (2 papers, 2017 to 2023). A tumor composed of atypical neoplastic, often pleomorphic cells that invade other tissues. "The association of the BEND3 protein with PICH at UFBs may indicate yet another pathway used by BEND3 towards cancer progression." (PMID 37509346, 2023). "In this manuscript, we have tried to establish the link between the transcription factor BEND3 and cancer." (PMID 37509346, 2023). "Elevated BEND3 expression is also reported in multiple cancer types across The Cancer Genomic Atlas (TCGA) Program." (PMID 37509346, 2023). "It is a possibility that BEND3 could also exhibit cancer-promoting effects and act together with this complex in the modulation of epigenetic marks at various loci to promote cancer development." (PMID 37509346, 2023). "BEND3 is reported to mediate a switch in the chromatin state from constitutive heterochromatin to facultative heterochromatin during embryonic development and cancer." (PMID 37509346, 2023). "This review summarizes the possible pathways via which the transcription factor BEND3 may serve as a driver for cancer development." (PMID 37509346, 2023). "While there is limited research on the role of BEND3 as a tumor suppressor or an oncogene and its potential role in cancer therapy is still emerging, several studies suggest that it may be involved in both the processes." (PMID 37509346, 2023). "Moreover, a few recent studies indicate BEND3 as a potential target for cancer therapy." (PMID 37509346, 2023). "Although the role of BEND3 in cancer progression is still emerging and gaining prominence, nonetheless, the exact mechanism is not yet fully understood." (PMID 37509346, 2023). "Since the specific mechanisms by which BEND3 may contribute to cancer progression are not yet fully elucidated, in this review, we have discussed the possible pathways BEND3 may take to serve as an oncogenic driver or suppressor." (PMID 37509346, 2023).
BEND3 also shares sentences with these, for which no sentence is quoted: acute myeloid leukemia (2 papers); autoimmune disease (1); cognitive decline (1); infection (1); ischemic stroke (1); metastatic disease (1).